HMGA2 (high mobility group AT-hook 2)
Diseases named in the same sentence as HMGA2 in open-access papers (continued):
Sharing a sentence is not in itself a finding about the gene and the disease.
pituitary adenomas (continued). "Since let-7 regulates HMGA2 expression in pituitary adenomas, let-7 may also take a role in pituitary adenoma invasion." (PMID 25548562, 2014). "The transgenic mice with overexpressed HMGA2 developed pituitary adenomas, indicating that HMGA2 may be involved in pituitary tumorigenesis." (PMID 25548562, 2014). "Consistently, HDAC1 activity associated to pRB is lower in cells and pituitary adenomas overexpressing HMGA2 than in mock-transfected cells and normal pituitary, respectively." (PMID 16914062, 2006). "Moreover, in vitro and in vivo observations have shown that HMGA proteins overexpression has an oncogenic activity, since effectively both HMGA1 and HMGA2 overexpression transforms mouse and rat fibroblasts, and both Hmga1 and Hmga2 transgenic mice develop NK-T cell lymphomas and pituitary adenomas." (PMID 32344629, 2020). "HMGA2 overexpression and the decrease of let-7 were significantly correlated with tumor proliferation, growth, invasion, and tumor grade, which lead to a hypothesis that let-7 may also function as a tumor suppressor in pituitary adenomas by targeting HMGA2." (PMID 25548562, 2014). "Thus, let-7, as a regulator of HMGA2, may exert its effects in cell cycle control of pituitary adenomas by targeting HMGA2." (PMID 25548562, 2014). "The interaction of HMGA2 with retinoblastoma protein (Rb1) activates E2F1, which is a driving force in pituitary adenoma formation in HMGA2 over-expressing mice." (PMID 36835656, 2023). "Previous studies revealed that the interaction between HMGA2 and pRB enhances the activation of E2F1 in pituitary adenomas." (PMID 33731207, 2021). "Consistent with previous observations, the overexpression of miR-16 reduced both HMGA1 and HMGA2 mRNA and protein levels in the GH3 rat pituitary adenoma cell line." (PMID 31979076, 2020). "Furthermore, it has been shown that HMGA2 (High Mobility Group AT-hook 2), which is a well-known non-transcription factor with oncogenic properties, is highly expressed in several benign tumors of mesenchymal origin, e.g., pituitary adenomas and several malignancies, including thyroid cancer." (PMID 29561759, 2018). "The targeting of HMGA2 by miR-370-3p was already described in the context of no-functional pituitary adenoma." (PMID 32443824, 2020). "For instance, CXCL12-regulated miR-370–3p acts as a tumor suppressor of nonfunctional pituitary adenomas via targeting HMGA2." (PMID 31703640, 2019). "Moreover, HMGA1 or HMGA2 overexpression is able to transform mouse and rat fibroblasts, and transgenic mice overexpressing either HMGA1 or HMGA2 develop haematopoietic malignancies and pituitary adenomas." (PMID 24728959, 2014). "HMGA2 overexpression was also found in non-functional and PRL-secreting pituitary adenomas." (PMID 40362297, 2025).
liposarcoma (26 papers, 2009 to 2025). A usually painless malignant tumor that arises from adipose tissue. "The amplification of several oncogenes, mainly CDK4, MDM2, and HMGA2, was involved in liposarcoma pathogenesis." (PMID 41531533, 2025). "In neoplasms originating from other tissues (e.g. liposarcoma) HMGA2 alteration and MDM2 amplification have also been described." (PMID 40338436, 2025). "Liposarcomas express specifically HMGA2, MDM2 and myxoid liposarcomas express specifically CD34 and DDIT13." (PMID 39862670, 2025). "Overexpression of HMGA2 coincided with elevated levels of H2A, H2B, H3, and H4 core histones in a subpopulation of dedifferentiated liposarcoma, again conferring a poor prognosis." (PMID 36835656, 2023). "Many genetic mutations have been reported in dedifferentiated liposarcomas, including mutations in MDM2, CDK4, high mobility group AT-hook 2 (HMGA2), fibroblast growth factor receptor substrate 2 (FRS2), and neuron navigator 3 (NAV3), all located in 12q13-15." (PMID 35008848, 2021). "Another mesenchymal tumorigenic mechanism allowing for the expression of full length HMGA2 transcripts has been described in well differentiated liposarcomas (WDLPS) and atypical lipomas (ALP)." (PMID 32365712, 2020). "We also identified previously reported fusions of SSX with SS18 in synovial sarcoma, as well as HMGA2 in liposarcoma." (PMID 28424409, 2017). "Among the amplified and overexpressed genes were MDM2, CDK4 and HMGA2, all well-known amplified targets in liposarcoma." (PMID 27409346, 2016). "Their pattern was similar to an analysis of 38 well-differentiated/dedifferentiated liposarcomas which revealed overexpression of both HMGA2 and MDM2 in all cases, but with an inconsistent amplification of CDK4 in 13% of cases." (PMID 23766666, 2013). "Because HMGA2 most frequently is rearranged in well-differentiated liposarcomas, border-line tumours resembling adipose tissue, most sarcoma cell lines, representing highly malignant cancers with a different tissue type, would not be appropriate to detect a phenotype when the gene is over-expressed." (PMID 20576167, 2010). "For instance, dedifferentiated liposarcoma was frequently diagnosed in patients with poor prognosis, and researchers have acknowledged this peculiarity is related to MDM2 and HMGA2 expression." (PMID 40870476, 2025). "Recently, it was shown that the other member of the HMGA family, i.e., HMGA2, is responsible for the increase in RD-HIST level in a subset of dedifferentiated liposarcoma." (PMID 36614035, 2022). "Reports on the amplification of chromosome 12q13–15, containing oncogenes MDM2, HMGA2 and CDK4 in about 90% of well and dedifferentiated liposarcoma led to the development of new targeted agents." (PMID 26887042, 2016). "The most evidence, to date, demonstrates an oncogenic role in dedifferentiated liposarcoma, like the atypical lipomatous tumor/well-differentiated liposarcoma, for MDM2, CDK4, HMGA2, and TSPAN31 (SAS)." (PMID 25713799, 2015). "Furthermore, all dedifferentiated liposarcomas (DDLPSs), well-differentiated liposarcomas (WDLPSs), and atypical lipomatous tumors (ALTs) present chromothripsis in the long arm of chromosome 12, where amplified CDK4, HMGA2, and MDM2 genes are localized." (PMID 40141463, 2025). "Therefore, HMGA2-mediated elevation of RD-HISTs were crucial events in determining the aggressiveness of DDLPS, which may serve as a biomarker for prognosis prediction for liposarcoma patients." (PMID 34206586, 2021). "Dedifferentiated liposarcoma is a high-grade non-lipogenic sarcoma that arises in a background of a pre-existing well-differentiated liposarcoma, harbouring a genomic amplification in the 12q13–15 region constituting the MDM2, CDK4 and HMGA2 genes." (PMID 29621151, 2018).
prostate carcinoma (25 papers, 2011 to 2025). A carcinoma that arises from epithelial cells of the prostate gland. "In our analysis, higher wild-type HMGA2 expression was associated with more advanced prostate cancer stages and higher Gleason grades." (PMID 41516076, 2025). "Herein we established a canine CT1258-EGFP-HMGA2 prostate cancer cell line stably overexpressing HMGA2 linked to EGFP and in addition the reference cell line CT1258-EGFP expressing solely EGFP to exclude EGFP-induced effects." (PMID 24914948, 2014). "For example, NEAT1 can regulate the epigenetics of target gene promoters to play the role of oncogenes, by increasing ACSL4 via sponging miR-34a-5p and miR-204-5p, or HMGA2 via sponging miR-98-5p, and was found significantly associated with prostate cancer prognosis." (PMID 35075375, 2022). "This study developed an Artificial Intelligence/Machine Learning (AI/ML)-assisted RISH quantification pipeline to evaluate expression patterns of High Mobility Group AT Hook-2 (HMGA2) in prostate cancer (PCa), focusing on racial disparities." (PMID 41516076, 2025). "In our previous study, we found that HMGA2 promoted the development and progression of prostate cancer by regulating epithelial–mesenchymal transition and matrix metalloproteinases." (PMID 34115920, 2021). "Intriguingly, overexpression of HMGA2 was found to upregulate the expression level of p-ERK in prostate cancer cells." (PMID 34844630, 2021). "Based on our previous study of prostate cancer, we detected the expression of HMGA2 in different cervical cancer cell lines and the normal cell line." (PMID 34115920, 2021). "Sustained expression of the epithelial phenotype was also observed in HMGA2-/- prostate cancer cells in which EMT was also inhibited." (PMID 32365712, 2020). "The proof for a molecular medical approach is demonstrated by highly efficient knock down of the oncogene HMGA2 in a rapidly proliferating prostate carcinoma in vitro model using siRNA." (PMID 25645721, 2015). "The knock down of the oncogene HMGA2 in canine prostate carcinoma cells was carried out successfully as shown by real time PCR expression analyses." (PMID 25645721, 2015). "In several malignant neoplasias including prostate cancer, high re-expression of HMGA2 is correlated with malignancy and poor prognosis." (PMID 24914948, 2014). "This CT1258-EGFP-HMGA2 cell line provides a valuable tool to further decipher the HMGA2-mediated molecular mechanisms of prostate cancer and to identify potential targets for development of novel therapies." (PMID 24914948, 2014). "The new fluorescent CT1258-EGFP-HMGA2 cell line is a stable tool enabling in vitro and in vivo analyses of the HMGA2-mediated effects on cells and the development and pathogenesis of prostate cancer." (PMID 24914948, 2014). "In conclusion, with the herein generated new fluorescent canine CT1258-EGFP-HMGA2 cell line a stable highly reproducible tool for further investigation of HMGA2-mediated cell proliferative effects in vitro and in vivo in prostate cancer is provided." (PMID 24914948, 2014). "Within this study, we analysed the described let-7-HMGA2 regulation mechanism in canine prostate cancer using the naturally HMGA2-overexpressing canine adenocarcinoma derived cell line CT1258 as an in vitro model." (PMID 24914948, 2014). "The gained insights of HMGA2-involvement in canine prostate cancer contribute to the identification and evaluation of novel therapeutic options." (PMID 24914948, 2014). "The identification of HMGA2 as a resistance marker could lead to more personalized treatment approaches, improving outcomes for patients with advanced prostate cancer." (PMID 39123360, 2024). "NEAT1 promotes HMGA2 expression in prostate cancer by acting as a sponge for miR-98-5p." (PMID 31868202, 2020). "In prostate cancer cells, silencing of HMGA2 could promote apoptosis, and inhibit migration, invasion and EMT." (PMID 28968424, 2017).
prostate carcinoma (continued). "As the dog represents a unique natural model for human prostate cancer, the insights concerning the involvement of HMGA2 in canine prostate cancer will provide benefit for both, humans and dogs, concerning the development of therapeutic strategies and the assessment of the treatment success." (PMID 24914948, 2014). "Furthermore, let-7a real-time PCR expression analyses were performed to investigate potential connections on the HMGA2-let-7-axis in canine prostate cancer." (PMID 24914948, 2014). "Moreover, the generated data adds functional data helping to understand the complex regulation mechanisms between HMGA2, let-7a and further selected targets in the progression of prostate cancer." (PMID 24914948, 2014). "In summary the new fluorescent canine CT1258-EGFP-HMGA2 cell line provides a valuable tool for further investigations on HMGA2-mediated proliferative effects and HMGA2 regulation mechanisms elucidating the development and pathogenesis of canine prostate cancer." (PMID 24914948, 2014). "In addition, an HMGA2 involvement in the induction of epithelial-to-mesenchymal transition (EMT) in the human prostate cancer cell line PC-3 was found." (PMID 24914948, 2014). "Our recent study reveals that the wild-type (WT) isoform of HMGA2 is associated with EMT, whereas the truncated HMGA2 isoform (TR) is implicated in increased cell proliferation and migration, which does not involve EMT in prostate cancer cells." (PMID 39123360, 2024). "In prostate cancer, AMPK plays a critical role in the promotive effect of HMGA2 on EMT." (PMID 38361784, 2024). "In another study of prostate cancer metastasis, overexpression of BTB and CNC Homology 1 (BACH1) transcription factor led to a significant decrease in let-7A expression and subsequent increase in HMGA2 which facilitated metastasis by promoting EMT." (PMID 32365712, 2020). "In prostate cancer, LBH589 indirectly inhibits the expression of HMGA2; thus, we wanted to determine whether LBH589 can also inhibit NF1 MPNST cell growth." (PMID 31053152, 2019). "However, the regulation of GPX4 by HMGA2 appears more complex in prostate cancer, where the truncated HMGA2 downregulates, rather than upregulates, GPX4." (PMID 39595619, 2024). "Interestingly, HMGA2, the strongest down-regulated gene in “A” (−15.88×), “whose silencing promotes apoptosis and inhibits migration and invasion of prostate cancer cells”, was not regulated in “B” and “C”." (PMID 34209090, 2021).
melanoma (24 papers, 2010 to 2025). A malignant, usually aggressive tumor composed of atypical, neoplastic melanocytes. "We discovered that IMP-3 expression was positively associated with HMGA2 expression in melanoma cells and tissues." (PMID 26796627, 2016). "Isolation of reporter positive melanoma-susceptible melanocytes from either Hmga2+/+ or Hmga2−/− mice was equally capable of melanoma formation when transplanted into recipient mice, illustrating that Hmga2 does not function intrinsically within the melanocyte but in the microenvironment." (PMID 29762513, 2018). "In addition, IMP-3 expression was positively associated with high mobility group AT-hook 2 (HMGA2) expression in melanoma." (PMID 26796627, 2016). "Conversely, IGF2BP3 bound and enhanced the mRNA stability of HMGA2 in the process of melanoma migration and invasion." (PMID 35676262, 2022). "IGF2BP3 promotes trophoblast invasion and migration via MMP9 mRNA stabilization and translation, and melanoma invasion and migration via HMGA2 mRNA stabilization and translation." (PMID 32293476, 2020). "miR-33b also reduces the migration and invasiveness of melanoma cell lines upon cordycepin exposure via targeting the HMGA2 3′UTR." (PMID 31979076, 2020). "When the Tyr::CreERT2; LSL-tdTomato; BrafCA/+; Ptenlox/lox mice were crossed with Hmga2−/− mice, there was a reduction in migrating MSCs and melanoma formation after UVB exposure." (PMID 29762513, 2018). "We observed that HMGA2 was predominantly expressed in melanoma metastases with a significant difference in two out of three studies (p = 3.6E-06, p = 0.301 and p = 2.4E-05), (SI)." (PMID 28852061, 2017). "HMGA2 was involved in cordycepin-mediated suppression of late-stage melanoma metastasis through the modulation of the activation of FAK and expression of EMT effectors." (PMID 26893968, 2016). "IMP-3 bound to and stabilized HMGA2 mRNA and improved the migration and invasion of melanoma cells by regulating HMGA2 expression." (PMID 26796627, 2016). "By targeting HMGA2 and Twist1, miR-33b attenuated melanoma migration and invasiveness upon cordycepin exposure." (PMID 25868853, 2015). "We also found that melanoma migration and invasiveness was mediated by miR-33b though directly targeting high mobility group AT-hook 2 (HMGA2), Twist1 and human zinc finger E-box binding homeobox 1 (ZEB1)." (PMID 25868853, 2015). "In the current study, we demonstrated that HMGA2 was involved in cordycepin-mediated suppression of late-stage melanoma metastasis through modulation of the activation status of FAK, Src, MLC and RhoA and expression of MMPs." (PMID 25868853, 2015). "We showed for the first time that targeting miRNA by cordycepin indicates a new mechanism of cordycepin-induced suppression of tumor metastasis and miR-33b/HMGA2/Twist1/ZEB1 axis plays critical roles in regulating melanoma dissemination." (PMID 25868853, 2015). "Another study on curcumin showed its inhibitory activity on the metastasis of melanoma cells through increasing miR-33b expression and concomitantly suppressing the expression of high-mobility group AT-hook 2(HMGA2)." (PMID 26305257, 2015). "Expression of cyclins-D1, D3 A and CDK4, as well as HMGA2 in adult and young adult-pediatric melanomas represents a central and future focus for our comparison of transgenerational melanoma specimens." (PMID 20302635, 2010). "Mechanically, inhibition of HMGA2 expression blocked the transition to Schwann-like melanoma fate." (PMID 40213656, 2025). "Their findings suggest that EGCG-induced upregulation of let-7b may repress tumor progression via suppression of HMGA2, thus inhibiting melanoma growth." (PMID 36829966, 2023). "In addition, the upregulation of miR-33b by EF24, which is a curcumin analogue, suppresses EMT and the induction of migration in melanoma cell lines via the targeting of HMGA2." (PMID 31979076, 2020).